ABCA13 (ATP binding cassette subfamily A member 13)
Diseases named in the same sentence as ABCA13 in open-access papers (continued):
Sharing a sentence is not in itself a finding about the gene and the disease.
cancer (12 papers, 2014 to 2025). A tumor composed of atypical neoplastic, often pleomorphic cells that invade other tissues. "There are few studies in literature regarding the role of ABCA13 in cancer, but they demonstrate a positive association between ABCA13 upregulation and unfavorable outcomes." (PMID 27366209, 2016). "Several studies have associated overexpression of ABCA13 with poor prognosis of cancer." (PMID 32881863, 2020). "Recently, several studies have associated overexpression of ABCA13 with poor prognosis of cancer." (PMID 27366209, 2016). "Moreover, the circRNA-miRNA system was established by bioinformatics approaches and successfully identified an interaction between circRNA ABCA13 and a cancer-related miRNA (miR-138-5p), which was also verified by qRT-PCR." (PMID 33413420, 2021). "ABCA13 gene is a member of ABC (ATP-binding cassette) family of transporters that plays a crucial role in the development of resistance by the efflux of anticancer agents outside of cancer cells." (PMID 27366209, 2016). "Abca13 is thought to be a marker of poor outcome in carcinoma patients as it could play a role in transport of xenobiotics and cause drug resistance." (PMID 27699085, 2016). "Besides the fact that the ABCA subfamily’s role as lipid transporters, the specific functions of ABCA1, ABCA13, and ABCD4 in cancer and specifically GBM are relatively unknown, which might warrant closer and more in-depth studies." (PMID 39861164, 2025). "Using the datasets in The Cancer Genome Atlas and Gene Expression Omnibus, we found upregulated ABC transporters that either negatively impacted survival in univariate analyses (ABCA1, ABCA13, ABCB9, ABCD4) or were independent negative prognosis factors for patients with GBM (ABCA13, ABCB9)." (PMID 39861164, 2025).
tumor (11 papers, 2016 to 2025). "However, the high E2F group presented increased frequencies of ABCA13, LRP1B, and ATP10B missense/nonsense mutations, suggesting a potential link between E2Fs and tumor-suppressor gene alterations." (PMID 40599792, 2025). "Particularly, elevated ABCA13 and EHZ2 expressions were positively correlated with tumor grade and disease progression of RCC." (PMID 28978010, 2017). "There were no significant changes in expression between the tumor and control tissues in the ABCB4, ABCA13, ABCC2, ABCC3, and ABCG2 genes." (PMID 36674773, 2023).
psychiatric disorder (4 papers, 2020 to 2021). A disorder characterized by behavioral and/or psychological abnormalities, often accompanied by physical symptoms. "ABCA13 gene mutations associated with psychiatric disorders impaired the subcellular localization and function of ABCA13." (PMID 33478937, 2021). "However, little is known about the molecular functions of ABCA13 or how they associate with psychiatric disorders." (PMID 33478937, 2021). "The discrepancy might be due to the low frequency of ABCA13 mutations in patients with these psychiatric disorders or the different populations in their studies." (PMID 34947986, 2021). "Furthermore, mutations in ABCA13 gene associated with psychiatric disorders disrupted the protein's subcellular localization and impaired cholesterol trafficking." (PMID 33478937, 2021). "We performed ABCA13 mutant analysis to determine the effects of mutations associated with psychiatric disorders on ABCA13 function, finding that abnormal psychological behaviors correlated with impairments in the subcellular localization of and cholesterol trafficking by ABCA13." (PMID 33478937, 2021). "Finally, mutations of ABCA13 associated with psychiatric disorders impaired the protein's subcellular localization and function." (PMID 33478937, 2021). "However, little is known about the molecular functions of ABCA13 or their association with psychiatric disorders." (PMID 33478937, 2021). "The impaired prepulse inhibition in Abca13 KO mice we observed suggests that the dysfunction of ABCA13 is related to the pathophysiology of psychiatric disorders." (PMID 33478937, 2021). "Further studies on the function of ABCA13 might lead to the development of novel therapeutic strategies for psychiatric disorders." (PMID 33478937, 2021). "Some scientists have focused on the relationship between ABCA13 and psychiatric disorders." (PMID 33299069, 2020).
neurological disorders (2 papers, 2010 to 2023). "ATP-binding cassette protein A13 (ABCA13) contributes to the risk of neurological disorders and showed to be a potential regulator of progression and response to the chemotherapy of mammary gland cancer." (PMID 36896338, 2023). "ABCA13 is expressed in human hippocampus and cortex and rare variants in this gene have been associated with neurological disorders." (PMID 20836839, 2010).
ABCA13 also shares sentences with these, for which no sentence is quoted: depression (2 papers); latent infections (2); lung carcinoma (2); prostate tumor (2); renal cell carcinoma (2); amyotrophic lateral sclerosis (1); attention deficit-hyperactivity disorder (1); basal cell carcinoma (1); cardiovascular disease (1); COVID-19 (1); eating disorder (1); frontotemporal dementia (1); gastric adenocarcinoma (1); infection (1); Lewy body dementia (1); mental disorder (1); Neonatal sepsis (1); neurodegenerative disease (1); non-small cell lung carcinoma (1); small cell lung carcinoma (1).